ZNF252P (zinc finger protein 252, pseudogene)
Synonyms: formerly ZNF252
Gene: Transcribed unprocessed pseudogene on chromosome 8 (144,976,190 to 144,999,723, reverse strand). Ensembl gene ENSG00000196922.
Diseases named in the same sentence as ZNF252P in open-access papers:
ZNF252P is named in the same sentence as 3 diseases in open-access papers, as found by Europe PMC text mining. Sharing a sentence is not in itself a finding about the gene and the disease. The quoted sentences say what the papers report.
ovarian carcinoma (1 paper, 2024). A malignant neoplasm originating from the surface ovarian epithelium. "However, a study of ZNF252P AS1 in ovarian cancer showed that miR-324-3P overexpression promotes the apoptosis of ovarian cancer cells by negatively regulating LY6K." (PMID 39727968, 2024).
cancer (2 papers, 2018 to 2025). A tumor composed of atypical neoplastic, often pleomorphic cells that invade other tissues. "A recent study identified ZNF252P as downregulated in multiple cancer types including PC." (PMID 40004558, 2025). "A major alteration for NACAP1 and ZNF252P was amplification in all 5 cancer types." (PMID 30071685, 2018). "Thus, we selected four pseudogenes (NACAP1, ZNF252P, FAM86B3P and RPL23AP53) for further analysis because they are top candidates that showed dysregulation in multiple cancer types." (PMID 30071685, 2018).
ZNF252P also shares sentences with these, for which no sentence is quoted: hypothyroidism (1 paper).